ASB2 (ankyrin repeat and SOCS box containing 2)
Diseases named in the same sentence as ASB2 in open-access papers (continued):
Sharing a sentence is not in itself a finding about the gene and the disease.
tumor (14 papers, 2019 to 2025). "Finally, we assessed tumor infiltration of adoptively transferred NK cells and found that ASB2-deficient NK cells had a decreased ability to infiltrate tumors in vivo using a xenograft tumor model." (PMID 33717133, 2021). "Deletion of ASB2 in hematopoietic cells inhibited the shortening of the colon and the tumor load in mice." (PMID 33833937, 2021). "Calcitriol or its analogues downregulated the expression of 4 genes related to the Th1 response in tumour tissue (Ifng (only calcitriol), Socs1, Tbx21 and Fasl) and upregulated 5 genes related to the Th2 response (Ccl11, Ptgdr2, Il9, Asb2 and Il5)." (PMID 31595196, 2019). "Overall, these results demonstrate that ASB2-deficiency phenocopies the AHR-deficiency in NK cells in terms of the ability of NK cells to migrate and infiltrate tumor tissue, thereby providing support for ASB2’s involvement in the AHR-mediated regulation of NK cell migration." (PMID 33717133, 2021). "Function analysis indicated that ASB2 may exert tumor-promoting roles by decreasing Th1, Th17, and cytotoxic CD8+ T cell response which are beneficial for protection against tumor progression." (PMID 33833937, 2021). "We found that, in concordance with the results observed in our TET2 KO models and in contrast to our observations in the TCGA dataset, methylation of the ASB2 promoter region was significantly increased in tumor samples as compared to normal (p = 0.04067, paired Wilcoxon signed-rank test)." (PMID 30917865, 2019). "In terms of anti-tumor, compound 32 inhibited AML cell proliferation (IC50 = 1.6 ~ 16 μM), induce apoptosis and upregulate ASB2 and RARA, direct targets of FTO, to exert anti-tumor effects." (PMID 38711100, 2024). "FTO negatively regulates the expression of Ankyrin Repeat and SOCS Box Containing 2 (ASB2) and Retinoic Acid Receptor Alpha (RARA), a cluster tumor suppressor target gene, by post-transcriptionally modulating its m6A abundance and then affecting its stability." (PMID 35422475, 2022). "In particular, FTO suppressed the expression of tumor suppressors, including ankyrin repeat and SOCS box containing 2 (ASB2) and retinoic acid receptor alpha (RARA) by eliminating m6A sites." (PMID 35628623, 2022). "We can find that the expression of GNG7, MXRA7, ASB2, and PDGFD in tumor samples is significantly lower than that in normal samples, while the expression of RPS6KA1, CHMP4C, APOL1, and LYPD3 is reverse." (PMID 36225190, 2022). "We validated the gene expression levels of AGER, DGKK, ASB2, TCP10L2, Lnc-ALCAM-3, and Lnc-TGFBR2-1 in HCC tumour tissue samples from mice treated with high-dose ascorbate by qPCR." (PMID 31754384, 2019). "The repression of ASB2 and TCP10L2 gene expression levels in HCC tumour mice treated with high-dose ascorbate compared to control was also verified." (PMID 31754384, 2019). "ASB2, on the other hand, does not show significant differences in expression among different immune cells, yet interestingly, its expression appears elevated in tumor cells from patients with a higher proportion of activated T cells." (PMID 40356925, 2025). "Intriguingly, out of seven key TET2-governed genes identified from our model exhibiting differential methylation in normal versus tumor samples in the TCGA at TET2-KO DMS-proximal probes, only one—ASB2—showed significantly decreased, rather than increased, methylation levels in cancer." (PMID 30917865, 2019).
cancer (11 papers, 2019 to 2025). A tumor composed of atypical neoplastic, often pleomorphic cells that invade other tissues. "A CCK-8 assay demonstrated that silencing ASB2 significantly reduced the proliferative ability of HEC-1A cells, while the overexpression construct showed the opposite effect, indicating that ASB2 expression can significantly inhibit cancer cell proliferation." (PMID 40356925, 2025). "However, ASB2 and HECW2; DET1, GAN, and HERW2 were expressed minimally in the LAML and DLBC cancers, respectively." (PMID 35711821, 2022). "Furthermore, we studied the protein level expression of ASB2, finding that the protein content of ASB2 is lower in cancer tissues compared to adjacent non-cancerous tissues." (PMID 40356925, 2025).
infection (3 papers, 2013 to 2025). The state of being infected such as from the introduction of a foreign agent such as serum, vaccine, antigenic substance or organism. "In contrast, Asb2 and Myct1 genes were both downregulated in the UB samples at both, 1 wk and 4 wks time points after infection." (PMID 36490282, 2022).
metabolic disease (1 paper, 2025). A congenital disorder (due to inherited enzyme abnormality) or acquired (due to failure of a metabolically important organ) disorder resulting from an abnormal metabolic process. "To evaluate the influence of increased muscle mass in Asb2 MKO male mice on potential benefits for metabolic diseases under lipid‐enriched conditions, we subjected these mice to a HFD for 4 weeks." (PMID 40641155, 2025).
myopathies (1 paper, 2025). "Our investigation in the skeletal muscle of mitochondrial polymerase γ mutant mice (Polg mut), an ageing‐associated myopathy model, revealed a significant decrease in lean body mass and Asb2 mRNA expression in QD muscle compared to age‐matched WT mice." (PMID 40641155, 2025). "Given desmin's crucial role in structural integrity, preventing muscle wasting and its association with mitochondrial dysfunction and impaired ATP‐dependent contraction in myopathies, we assessed mitochondrial function in Asb2 MKO muscle." (PMID 40641155, 2025).
ASB2 also shares sentences with these, for which no sentence is quoted: acute lymphoblastic leukemia (2 papers); acute promyelocytic leukemia (1); benign prostate hyperplasia (1); cardiac disease (1); cervical cancer (1); colorectal cancer (1); diffuse large B-cell lymphoma (1); gastric cancer (1); glaucoma (1); Glucose intolerance (1); hepatoma (1); Hip dysplasia (1); lung adenocarcinoma (1); melanoma (1); osteogenesis imperfecta (1); prostate carcinoma (1); thyroid carcinoma (1); Treacher-Collins syndrome (1).